PGF (placental growth factor)
Diseases named in the same sentence as PGF in open-access papers (continued):
Sharing a sentence is not in itself a finding about the gene and the disease.
preeclampsia (continued). "Importantly, the soluble-fms-like tyrosine kinase-1 (sFlt-1)/placental growth factor (PlGF) ratio, a widely used biomarker for preeclampsia, remains unaffected by RA disease activity or sulfasalazine use, and a threshold value of ≤38 retains its predictive value in this population." (PMID 41003109, 2025). "Therefore, uterine artery Doppler and biochemical markers of PAPP-A and placental growth factor (PLGF) suggested by the FMF prediction model for gestational hypertension might require another cost for application of the FMF model in high-risk pregnant women." (PMID 37374113, 2023). "Screening a combination of maternal factors and measuring mean arterial pressure, uterine pulsatility index, and serum placental growth factor may predict 90% of early preeclampsia cases, before 32 weeks, and 75% of preterm preeclampsia cases, before 37 weeks, with a 10% false-positive rate." (PMID 35807200, 2022). "We have also not assessed the circulating soluble fms-like tyrosine kinase-1 (sFlt-1) and placental growth factor (PlGF), the diagnostic markers of preeclampsia and we have not measured the other important vascular endothelial dysfunction markers such as vascular endothelial growth factor (VEGF)." (PMID 35821033, 2022). "It is well known that preeclampsia is closely associated with placental dysfunction characterized by altered maternal and placental levels of angiogenic factors like vascular endothelial growth factor (VEGF) and placental growth factor (PlGF) and its receptors fms-like tyrosine kinase-1 (Flt-1)." (PMID 31443707, 2019). "We assessed whether adding the biomarkers Pregnancy Associated Plasma Protein-A (PAPP-A) and Placental Growth Factor (PlGF) to maternal clinical characteristics improved the prediction of a previously developed model for gestational hypertension in a cohort of Ghanaian pregnant women." (PMID 29587776, 2018). "An imbalance of pro-angiogenic and anti-angiogenic factors in the maternal circulation has been demonstrated during preeclampsia, specifically increased levels of the anti-angiogenic soluble fms-like tyrosine kinase 1 (sFlt-1), and reduced levels of pro-angiogenic placental growth factor (PlGF)." (PMID 27243815, 2016). "Similarly, cord PGF levels were also lower in preterm infants born to mothers with preeclampsia." (PMID 24073247, 2013). "It has been associated with changes in placental angiogenesis, affecting the expression of placental growth factor (PLGF) and vascular endothelial growth factor (VEGF), which can lead to preeclampsia." (PMID 41596374, 2026). "A model based on the soluble Fms-like tyrosine kinase-1/placental growth factor ratio, gestational age, and the urinary protein-to-creatinine ratio (PRERISK calculator) has been developed to predict preeclampsia-related maternal-fetal complications." (PMID 40238908, 2025). "This is comparable to placental growth factor (PlGF, AUROC 0.77), a widely used biomarker of preeclampsia which has also been proposed as a biomarker of FGR and placental insufficiency." (PMID 40694862, 2025). "In contrast, placental growth factor (PLGF) levels gradually increase during pregnancy, showing high sensitivity and specificity in predicting preeclampsia." (PMID 40585732, 2025). "The observed differences in angiogenic capacity are consistent with previous studies showing that lower levels of placental growth factor (PlGF) and VEGF and higher levels of sFlt1 determine the antiangiogenic properties of serum in preeclampsia." (PMID 38742198, 2024). "Decreased expression of VEGFA, PGF, and KDR mRNA in placentas from pregnancies complicated by gestational hypertension was also observed, as well as reduced expression of VEGFA mRNA in placentas from pregnancies complicated by SGA with normal pressure." (PMID 38238614, 2024). "Decreased VEGF and placental growth factor (PlGF) mRNA were observed in BPH/5 placentas at E10.5, while sFLT-1 mRNA was significantly increased, consistent with preeclampsia symptoms." (PMID 37089425, 2023).
preeclampsia (continued). "The exact aetiology for preeclampsia is still unknown, but the evolution of immunology in recent years greatly contributes to the idea of uteroplacental disorders based on oxidative stress, including cytokines (e.g., sFlt-1-soluble fms-like tyrosine-kinase-1, PlGF-placental growth factor)." (PMID 37239851, 2023). "The group of Ananth Karumanchi were the first to show that women with preeclampsia have an increased placental expression of soluble FMS-like tyrosinekinase-1 (sFlt-1) and a decreased expression of placental growth factor (PlGF)." (PMID 36566477, 2023). "The two most studied and implicated biomarkers, especially in relation to the development of preeclampsia, are soluble FMS-like tyrosine kinase-1 (sFlt-1) and placental growth factor (PlGF)." (PMID 37007771, 2023). "Research on the pathogenesis of preeclampsia has unveiled substantial pivotal molecule factors, like soluble endoglin (sEng), soluble FMS-like tyrosine kinase-1 (sFlt-1), placental growth factor (PlGF), and vascular endothelial growth factor (VEGF)." (PMID 35528613, 2022). "Placental growth factor (PlGF) has a synergistic angiogenic effect interacting with the VEGF receptor (VEGFR-1), therefore decreasing from the first trimester in preeclampsia." (PMID 35631313, 2022). "The model replicates human preeclampsia symptoms with hypertension accompanied by increased circulating VEGF, sEng, Flt1, and placental growth factor (PlGF), plus elevated inflammatory cytokines and IUGR." (PMID 30984163, 2019). "Placental growth factor (PIGF) is an angiogenic factor and low concentrations have been observed in pregnant women who develop preeclampsia." (PMID 29587776, 2018). "Placental growth factor (PGF), soluble fms-like tyrosine kinase 1 (sFLT1) and asymmetric dimethylarginine (ADMA) are involved in the pathogenesis of preeclampsia." (PMID 25906026, 2015). "Angiogenic factors like placental growth factor (PlGF) and vascular endothelial growth factor (VEGF) have been found to be reduced in patients who develop preeclampsia." (PMID 26473833, 2015). "Increasing circulating soluble Flt-1, a soluble form of vascular endothelial growth factor (VEGF) receptor-1, which can bind both VEGF and placental growth factor (PGF), plays an important role in the pathogenesis of preeclampsia." (PMID 26588850, 2015). "Based on the findings in preeclamptic women, assays that measure s-Flt, PGF, and VEGF have been touted as potential tools to differentiate preeclampsia from other categories of hypertension in pregnancy." (PMID 22685661, 2012). "However, it may prove to be more informative when coupled with other biomarkers of PM, as is the case for preeclampsia, where the utility of sEng as a prognostic biomarker is strengthened when combined with measurements of soluble Flt-1 and placental growth factor." (PMID 21966395, 2011). "sFlt-1 is a soluble receptor for the vascular endothelial growth factor (VEGF) that binds to Placental Growth factor (PlGF) and VEGF receptors, thereby blocking their angiogenic function in the maternal circulation, leading to early onset preeclampsia before 34 weeks of gestation." (PMID 40265443, 2025). "Although biomarkers such as placental growth factor (PlGF) are used clinically to aid diagnosis in some clinical settings–particularly for preterm preeclampsia–there remains a lack of effective biomarkers to identify fetal growth restriction." (PMID 40694862, 2025). "Preeclampsia is attributed to an imbalance of placental-derived circulating pro-angiogenic (vascular endothelial growth factor, VEGF; placental growth factor, PlGF; membrane-bound endoglin, ENG) and anti-angiogenic (soluble fms-like tyrosine kinase 1, sFLT1; soluble endoglin, sENG) factors." (PMID 41416997, 2025).
preeclampsia (continued). "Serum placental circulating factors, specifically soluble vascular endothelial growth factor receptor 1 (sFlt-1) and placental growth factor (PLGF), have been identified as potentially significant markers for predicting early-onset preeclampsia in the first and second trimesters of pregnancy." (PMID 39056593, 2024). "The ratio of soluble fms-like tyrosine kinase 1 (sFlt-1) to placental growth factor (PlGF) can be used to exclude preeclampsia (if low: excellent negative predictive value); it is helpful to discriminate HELLP from aHUS after 20 weeks of gestation." (PMID 35160242, 2022). "Anti-angiogenic factors including soluble fms-like tyrosine kinase-1 (sFlt-1) and soluble endoglin (sEng) are upregulated in preeclampsia and induce their effects by blocking the angiogenesis-promoting actions of vascular endothelial growth factor (VEGF) and placental growth factor (PlGF)." (PMID 33879252, 2021). "We investigated the predictive value of the soluble fms-like tyrosine kinase-1 (sFlt-1)-to-placental growth factor (PlGF) ratio for poor neonatal outcomes of SGA neonates in the absence of preeclampsia." (PMID 33663078, 2021). "Although this is a well-characterised group of women (see S1 Data demographic and Clinical information worksheets), we have no data on circulating angiogenic factors (e.g., placental growth factor) to confirm the diagnosis of preeclampsia." (PMID 32463837, 2020). "Using vasoactive markers, placental growth factor (PlGF) and soluble vasoactive endothelial growth factor reseptor-1 (s-Flt1), preeclampsia can be divided into angiogenic and non-angiogenetic subgroups." (PMID 28350823, 2017). "This prospective observational study compare urine nephrin:creatinine ratio (NCR, ng/mg) with serum soluble fms-like tyrosine kinase-1:placental growth factor ratio (FPR, pg/pg) for preeclampsia (PE) prediction among unselected asymptomatic pregnant women in 2nd trimester." (PMID 27874074, 2016). "Although the pathophysiology of preeclampsia has not been established, placental growth factor (PlGF) is believed to be a key factor." (PMID 26214510, 2015). "Increasing circulating soluble Flt-1, a soluble form of vascular endothelial growth factor (VEGF) receptor-1 which can bind both VEGF and placenta growth factor (PGF), resulting impairment of angiogenic state was thought to be responsible for the pathogenesis of preeclampsia." (PMID 24073247, 2013). "A preeclampsia biomarker test (soluble Fms-like tyrosine kinase-1 (sFLT-1)/placental growth factor (PlGF), Labcorp test 486226) was sent and returned negative (sFLT-1 1856, PlGF 239.5, ratio 8)." (PMID 39901964, 2025). "The imbalance between angiogenic growth factors such as placental growth factor (PlGF) and vascular endothelial growth factor (VEGF) and the antiangiogenic factor soluble fms-like tyrosine kinase-1 (sFlt-1) plays a central role in the pathophysiological mechanisms of preeclampsia." (PMID 41517251, 2025). "Importantly, placental growth factor (PlGF) and vascular endothelial growth factor (VEGF) exhibit no causal association with preeclampsia." (PMID 39286274, 2024). "The PRediction of short-term Outcomes in preGNant wOmen with Suspected preeclampsIa Study (PROGNOSIS) Asia validated the use of the soluble fms-like tyrosine 1/placental growth factor (sFlt-1/PlGF) ratio cutoff value of ≤38 to rule out the occurrence of preeclampsia in the short term in Asian women." (PMID 33594274, 2021). "Two prospective multicenter studies demonstrated that a soluble fms-like tyrosine kinase 1 (sFlt-1)/placental growth factor (PlGF) ratio cutoff of ≤38 can rule out preeclampsia within 1 week with a negative predictive value (NPV) of 99.3% (PROGNOSIS) and 98.6% (PROGNOSIS Asia)." (PMID 33727707, 2021). "National guidelines have approved placental growth factor (PlGF) testing to rule out suspected preeclampsia, but the utility of repeated PlGF measurement is unknown." (PMID 32017014, 2020).
preeclampsia (continued). "Placental growth factor (PGF), is low in preeclampsia; reduced levels may affect brain development." (PMID 31243296, 2019). "A biochemical index much studied in recent years, the soluble fms-like tyrosine kinase-1/placental growth factor (sFlt1/PlGF) ratio, may be a valuable tool for initial assessment in patients with a TMA in pregnancy to rule out preeclampsia/HELLP syndrome." (PMID 38396391, 2024).
Hypertension (157 papers, 2010 to 2026). The presence of chronic increased pressure in the systemic arterial system. "It is associated with hypertension and an increase in angiogenic factor soluble fms-like tyrosine kinase-1 (sFlt-1)/placental growth factor." (PMID 40746439, 2025). "Four proteins (CXCL1, CD84, HO1, and PGF) were linked to disorders of blood pressure, including (early-onset) hypertension." (PMID 38958674, 2024). "Some studies have found that maternal age and family history of hypertension are also associated with the development of PE, while others have suggested that changes in the concentration of placental growth factor (PLGF) are a key factor in the development of PE." (PMID 38260145, 2023). "In terms of analysing interactions between vitamin D and acknowledged risk factors for PE and pregnancy-induced hypertension, maternal placental growth factor (PlGF) levels were low among women presenting with low vitamin D status in the early and late second trimester." (PMID 29494538, 2018). "First, excess placental soluble Flt-1 (sFlt-1) neutralises vascular endothelial growth factor (VEGF) and placental growth factor (PlGF), producing an angiogenic deficit that drives endothelial dysfunction, hypertension, proteinuria and end organ injury." (PMID 41897371, 2026). "An imbalance between soluble fms‐like tyrosine kinase‐1 (sFlt‐1) and placental growth factor (PlGF) is characteristic of the progression of hypertensive disorder of pregnancy (HDP) to pre‐eclampsia (PE)." (PMID 40992360, 2025). "sFlt-1 inhibits these actions by binding to VEGF and placental growth factor (PlGF) in the circulating blood, resulting in vasoconstriction-induced hypertension, organ damage, and thrombocytopenia due to thrombus formation." (PMID 39329931, 2024). "It has also been suggested that a splenic factor, the placental growth factor (PlGF), mediates a sympathetic stimulation of the spleen leading to costimulation and deployment in target organs of T cells promoting the onset of hypertension." (PMID 37568294, 2023). "sFlt-1 has anti-mitogenic properties on endothelial cells by trapping VEGF and placental growth factor (PlGF) leading to hypertension and proteinuria." (PMID 30972026, 2019). "Current diagnostic approaches predominantly depend on late-onset clinical features (e.g., proteinuria, hypertension) and suboptimal biomarkers such as soluble fms-like tyrosine kinase-1 to placental growth factor (sFlt-1/PlGF) ratio, which significantly constrains timely clinical intervention." (PMID 40552285, 2025). "In the framework of hypertension, pressure overloading of the heart stimulates the activation of the sympathetic nervous system, which, in turn, activates dorsal vagal complex and splenic innervation, driving placental growth factor secretion (PlGF)." (PMID 40948785, 2025). "Maintenance of normal values for the serum-soluble FMS-like tyrosine kinase 1 to placental growth factor ratio and the uterine artery pulsatility index (UtAPI) is characteristic of patients with this pathology, even in the presence of hypertension and other PE-like manifestations." (PMID 38525192, 2024). "After adjusting for the effects of high blood pressure and an elevated soluble fms-like tyrosine kinase-1 (sFlt-1)/placental growth factor (PlGF) ratio at 18–24 weeks, decreased gal-1 expression is considered to be a risk factor for the development of GH and PE in pregnancy." (PMID 36077508, 2022). "Placental Growth Factor (PlGF) influences a neuro-immunological pathway in the spleen which may contribute to hypertension." (PMID 31416428, 2019). "Future investigation should be focused on key factors among other inflammatory mediators and growth factors such as vascular endothelial growth factor, placental growth factor, and basic fibroblast growth factor, all involved in pathogenesis of pregnancy-induced hypertension." (PMID 30622610, 2018).
Hypertension (continued). "It has recently been demonstrated that the angiogenic placental growth factor (PlGF) seems to impact a neuro-immunological pathway in the spleen that may contribute to hypertension suggesting that hypertension may be in part an immunologically mediated disease." (PMID 31416428, 2019). "Based on their disease–gene associations, these biomarkers are involved in vascular inflammation (HO-1, LPL, PAPPA, ADAMTS13, ADM, PGF, and GDF-2), hypertension, and arterial disease (PAPPA, ADAMTS13, ADM, and PGF)." (PMID 35327515, 2022). "We demonstrated that placental growth factor (PlGF) is a crucial player of this pathway, thus suggesting that, even the interaction between this signaling pathway and PI3Kγ could be investigated in search of mechanisms that couple vascular and immune alterations contributing to hypertension." (PMID 27834808, 2016). "At week 28, the patient had neither hypertension nor proteinuria, but her soluble Fms-like tyrosin kinase-1 (sFLT1) to placental growth factor (PlGF) ratio was slightly elevated (sFLT1/PlGF, 92; normal values < 38)." (PMID 39995752, 2025). "Concentrations of placental growth factor at 28 weeks of gestation have correlated inversely to maternal gestational BP trajectory, independent of the diagnosis of pregnancy‐induced hypertension, and have been suggested to be a mediator of cardiovascular health in pregnancy." (PMID 34978718, 2022).